CAVIN4 (caveolae associated protein 4)
Description:
Modulates the morphology of formed caveolae in cardiomyocytes, but is not required for caveolar formation. Facilitates the recruitment of MAPK1/3 to caveolae within cardiomyocytes and regulates alpha-1 adrenergic receptor-induced hypertrophic responses in cardiomyocytes through MAPK1/3 activation. Contributes to proper membrane localization and stabilization of caveolin-3 (CAV3) in cardiomyocytes (By similarity). Induces RHOA activation and activates NPPA transcription and myofibrillar organization through the Rho/ROCK signaling pathway.
Synonyms: MURC; cavin-4
Tractability: Antibody: UniProt places it where antibodies can reach, with high confidence; its Gene Ontology location is reachable by antibodies, with high confidence; the Human Protein Atlas places it where antibodies can reach.
Gene: Protein-coding gene on chromosome 9 (100,578,033 to 100,588,402, forward strand). Ensembl gene ENSG00000170681.
Subcellular location: Cytoplasm, myofibril, sarcomere; Cytoplasm; Cytoplasm, cytosol; Cell membrane, sarcolemma; Membrane, caveola; Cell membrane
Subcellular location (Human Protein Atlas): Golgi apparatus; Plasma membrane; Nucleoplasm
Gene Ontology:
Molecular function: protein binding
Biological process: regulation of gene expression
Cellular component: caveola; plasma membrane; cytoplasm; cytosol; sarcolemma; sarcomere; Z disc
Genetic constraint (gnomAD): Loss-of-function variants: 11 observed, 20.82 expected, observed/expected ratio (o/e) 0.53, 90% interval 0.33 to 0.88. The upper end of that interval is the gene's LOEUF score, 0.88, which puts it in group 3 of 6, group 1 being the genes least tolerant of losing a copy. Missense variants: 459 observed, 457.34 expected, observed/expected ratio (o/e) 1, 90% interval 0.93 to 1.08. Synonymous variants: 173 observed, 174.25 expected, observed/expected ratio (o/e) 0.99, 90% interval 0.88 to 1.13.
Homologues: Orthologues: chimpanzee CAVIN4 (99% identical), dog CAVIN4 (88% identical), guinea pig CAVIN4 (85% identical), pig CAVIN4 (85% identical), rabbit CAVIN4 (84% identical), mouse Cavin4 (82% identical), rat Cavin4 (82% identical), zebrafish cavin4a (37% identical), zebrafish cavin4b (37% identical). Paralogues in human: CAVIN2 (29% identical), CAVIN1 (27% identical), CAVIN3 (17% identical).
Diseases named in the same sentence as CAVIN4 in open-access papers:
CAVIN4 is named in the same sentence as 25 diseases in open-access papers, as found by Europe PMC text mining. Sharing a sentence is not in itself a finding about the gene and the disease. The quoted sentences say what the papers report.
dilated cardiomyopathy (3 papers, 2015 to 2021). Cardiomyopathy which is characterized by dilation and contractile dysfunction of the left and right ventricles. "Cavin4 mutations have been described in dilated cardiomyopathy patients and there is evidence that Cavin4 recruits ERK in cardiomyocytes." (PMID 33591275, 2021). "CAVIN4 mutations have previously been linked to Dilated Cardiomyopathy (DCM)." (PMID 27294373, 2016).
cardiac hypertrophy (2 papers, 2016 to 2019). "A Cavin4/Cav3 complex co-localizes with α1-adrenergic receptors (α1-AR) in cardiomyocytes and α1-AR-induced cardiac hypertrophy is attenuated in Cavin4/Murc mutant mice." (PMID 27294373, 2016).
cardiomyopathy (2 papers, 2016 to 2021). A disease of the heart muscle or myocardium proper. "Given the interdependence between Cavin and Caveolin protein expression and distribution, the role of Cavin4 in cardiomyopathy should be studied further." (PMID 27294373, 2016).
breast carcinoma (1 paper, 2021). "However, it should be noticed that the expression levels of CAV3 and CAVIN4 in both cancer tissues and normal tissues were rather low, indicating a limited role of these two proteins in the tumorigenesis and progression of breast cancer." (PMID 34513683, 2021).
leukemia (1 paper, 2022). A malignant (clonal) hematologic disorder, involving hematopoietic stem cells and characterized by the presence of primitive or atypical myeloid or lymphoid cells in the bone marrow and the blood. "In particular, higher CAVIN4 expression was significantly associated with better OS in leukemia (p = 0.048)." (PMID 35722492, 2022). "Interestingly, low expression of CAVIN1 and CAVIN4 is correlated with poorer outcome but low CAVIN2 expression is associated with a significantly better leukemia prognosis in leukemia." (PMID 35722492, 2022). "Finally, we investigated the prognostic value of CAVIN1, CAVIN2, CAVIN3, and CAVIN4 in leukemia using the R programming language to assess data from LinkedOmics." (PMID 35722492, 2022). "The expression of CAVIN1 and CAVIN2 is higher in myeloid leukemia than lymphoblastic leukemia, while CAVIN4 expression is just the opposite in leukemia." (PMID 35722492, 2022). "In particular, overexpressed CAVIN4 was associated with a better overall survival (OS), as we expected, but there was obviously better OS with high vs. low expression of CAVIN2 in leukemia (p = 0.017) by R-programing in our report." (PMID 35722492, 2022). "We might hypothesize that the Cavin family, especially CAVIN2 and CAVIN4, could be potential markers of the clinicopathological parameters of patients with different types of leukemia." (PMID 35722492, 2022). "We then used the GEPIA and BloodSpot database to validate the unexpected result and found that high CAVIN2 expression was significantly associated with poorer OS in leukemia (p is 0.037 and 0.022 individually), but the trend was not significant for CAVIN1, CAVIN3 and CAVIN4." (PMID 35722492, 2022).
lymphoblastic leukemia (1 paper, 2022). "All Cavin family members were significantly downregulated in lymphoblastic leukemia except for CAVIN4." (PMID 35722492, 2022). "However, compared with lymphocytic leukemia, CAVIN4 expression is relatively higher in lymphocytic leukemia than that in myeloid leukemia, especially in acute lymphoblastic leukemia." (PMID 35722492, 2022).
lymphocytic leukemia (1 paper, 2022). "We found that the expression level of both CAVIN1 and CAVIN2 in myeloid leukemia is higher than that in lymphocytic leukemia, while the expression of CAVIN4 is higher in lymphocytic leukemia." (PMID 35722492, 2022).
scrapie (1 paper, 2025). A fatal disease of the nervous system in sheep and goats, characterized by pruritus, debility, and locomotor incoordination. "Cavin4, the caveolar protein in membrane lipid rafts, has been claimed to be required for the proposed conversion of normal host PrP into its misfolded, presumably infectious scrapie amyloid form." (PMID 40434970, 2025).
infection (2 papers, 2015 to 2025). The state of being infected such as from the introduction of a foreign agent such as serum, vaccine, antigenic substance or organism. "This CJ imprinted downregulation of Prnp, PrP, and PrP amyloid, in addition to downregulated Cavin4, failed to suppress high levels of infection." (PMID 40434970, 2025).
cancer (1 paper, 2021). A tumor composed of atypical neoplastic, often pleomorphic cells that invade other tissues. "As a sub-structure of caveolae, CAV3 only revealed association with CAVIN4, which were both little expressed in cancer cells." (PMID 34513683, 2021).
tumor (1 paper, 2015). "For this purpose, IHC analysis carried out on serial tumor sections showed that MURC/cavin-4 staining consistently overlaps that of Cav-3 in a significant number of foci/cells." (PMID 26086601, 2015). "In addition, we have investigated MURC/cavin-4 expression in vitro by means of human cell lines and mouse primary tumor cultures established from conditional transgenic mice." (PMID 26086601, 2015). "We found MURC/cavin-4 to be expressed, often concurrently with Cav-3, in mouse and human RMS, as demonstrated through in silico analysis of gene datasets and immunohistochemical analysis of tumor samples." (PMID 26086601, 2015).
CAVIN4 also shares sentences with these, for which no sentence is quoted: Arrhythmia (1 paper); atrial fibrillation (1); cardiac arrhythmia (1); cardiac disease (1); centronuclear myopathies (1); chronic heart failure (1); Cutaneous abscess (1); fibrosis (1); heart failure (1); invasive breast carcinoma (1); myeloid leukemia (1); peritonitis (1); pulmonary hypertension (1); rhabdomyosarcoma (1).